BTK (Bruton tyrosine kinase)
Diseases named in the same sentence as BTK in open-access papers (continued):
Sharing a sentence is not in itself a finding about the gene and the disease.
myeloma (continued). "BTK has been shown to be strongly expressed in myeloma cells and selectively expressed in osteoclasts but not in osteoblasts." (PMID 34201396, 2021). "Moreover, the Bruton tyrosine kinase (BTK) signal pathway and Connexin-43 were also involved in the MSC and MM cell interaction, which increased myeloma stemness and tumour cell proliferation." (PMID 29535427, 2018). "Although our data strongly support synergistic cytotoxicity between LU-102 and ibrutinib on myeloma cells, involving at least partly the NFkB pathway, BTK is likely not the only relevant target of ibrutinib in this setting." (PMID 26099967, 2015). "Thus, it seems plausible that BTK inhibitors, such as ibrutinib, dampen Wnt/β-catenin and AKT-dependent mechanisms of myeloma “stemness”." (PMID 26415231, 2015). "Clearly, BTK is upstream of several “stemness” pathways in myeloma, including WNT, Notch and AKT, but agreement does not exist whether BTK activates or inhibits Wnt/β-catenin signaling." (PMID 26415231, 2015). "Also, pathological BTK is especially up-regulated in CLL and myeloma but not in other types of cancer." (PMID 34077419, 2021).
marginal zone lymphoma (32 papers, 2018 to 2026). A usually indolent mature B-cell lymphoma, arising from the marginal zone of lymphoid tissues. "Some studies have shown that mutations in BTK and PLCG2 are the most common mechanisms of resistance to ibrutinib in CLL, WM, and marginal zone lymphoma (MZL)." (PMID 37048814, 2023). "Based on the activity observed in DLBCL and MCL cell lines, we also tested the compound in two marginal zone lymphoma (MZL) cell lines (Karpas1718 and VL51) and their derivatives with acquired resistance to PI3K inhibitors, BTK inhibitors, and BCL2 inhibitors." (PMID 40563683, 2025). "BTK inhibitors like ibrutinib and acalabrutinib have been approved for B cell malignancies like CLL, MCL, marginal zone lymphoma (MZL), and WM." (PMID 31345247, 2019).
Immunodeficiency (31 papers, 2012 to 2026). Failure of the immune system to protect the body adequately from infection, due to the absence or insufficiency of some component process or substance. "This review examines the mechanistic basis of BTK inhibitor-associated immune dysfunction, compares generational differences in selectivity and safety profiles, and provides evidence-based recommendations for infection risk mitigation in clinical practice." (PMID 42192981, 2026). "Again, demonstrating the significant difference between human and murine B cell development and the role of BTK therein, mutation of R28 in human BTK resulted in pronounced XLA immunodeficiency." (PMID 39120280, 2024). "Fruman and colleagues found that these PKCβ knockout mice had immune disorders similar to individuals with deficiencies in Bruton tyrosine kinase (Btk) or X-linked immunodeficiency." (PMID 39445011, 2024). "Known pathogenic variants of BTK (Arg255Ter, Gly594Arg, and Trp281Ter) were detected from three patients (Cases 1, 6, and 14) with immunodeficiency." (PMID 37325673, 2023). "P4 is also the only patient with a BTK pathogenic variant that has been associated in some cases with B cell lymphopenia with normal immunoglobulin levels and a selective polysaccharide immunodeficiency." (PMID 37063907, 2023). "Consistent with this notion, whereas loss-of-function mutations of BTK result in immunodeficiency, loss-of-function mutation of LYN rather results in autoimmunity." (PMID 35440579, 2022). "Genetically defined immunodeficiencies were first described with the identification of BTK mutations in X-linked (Bruton’s) agammaglobulinemia, and subsequently expanded to include several B-cell receptor genes, including BLNK, μ heavy chain, and CD79A/B5,38." (PMID 31409799, 2019). "Bruton tyrosine kinase (BTK) is a key enzyme in B-cell development whose improper regulation causes severe immunodeficiency diseases." (PMID 29142210, 2017). "BTK deficiency blocks the transformation of progenitor B cells into pre-B cells, mature B cells and inhibits the production of mature B cells, leading to immunodeficiency diseases." (PMID 39993065, 2025). "Similar results were observed for four other genes on chromosome X, KDM6A, which is somatically involved in BL39, and BTK, SH2D1A40, and XIAP41, which are indirectly linked with BL risk via X-linked immunodeficiencies related to EBV." (PMID 38057307, 2023). "The recent discoveries and significance of BTK inhibitors in the treatment of various immune diseases are summarized in this review." (PMID 35628931, 2022). "The results of preclinical studies from autoimmune animal models are promising, and several phase 1 and phase 2 clinical trials with BTK inhibitors were initiated in patients with immune disorders, such as RA, SLE, SM, PV, AIHA, ITP, and GVHD." (PMID 35628931, 2022). "BTK is a multidomain tyrosine kinase and in the decades since Dr. Bruton’s discovery it has become clear that genetic defects in the regulatory domains or the catalytic domain can lead to immunodeficiency." (PMID 34249912, 2021). "Furthermore, the role of BTK mediated signaling pathway in the auto-immune diseases is still under extensive study yet and a more selective inhibitor will greatly facilitate the basic mechanistic study than the non-selective inhibitors." (PMID 28352114, 2017). "For example, a patient with autoinflammatory features may require a selection that favors genes associated with proinflammatory diseases such as MEFVand TNFAIP3, whereas a patient with mainly immunodeficiency may have preferential scoring for genes such as BTK and DOCK8." (PMID 31388879, 2019). "Although novel drugs such as BTK inhibitors, JAK inhibitors and ROCK2 inhibitors expand treatment options, irreversible fibrotic progression and severe immune dysfunction along with serious infectious complications remain challenging." (PMID 39403509, 2024).
Immunodeficiency (continued). "Our study provides evidence for an expanded role of BTK in T cells for optimal TCR-dependent signaling and reveals the role of BTK in the pathology of T-cell-mediated immune diseases." (PMID 31431692, 2020).
CNS lymphoma (30 papers, 2020 to 2025). "A pharmaceutical compound that is more commonly used in the treatment of central nervous system lymphoma is Ibrutinib, which is a Bruton tyrosine kinase (BTK) inhibitor." (PMID 41562074, 2025). "Whole‐brain radiotherapy, BTK inhibitors and immunotherapy have demonstrated efficacy in treating CNS lymphoma." (PMID 41347016, 2025). "Tirabrutinib is a highly selective and highly active BTK inhibitor developed in Japan for the treatment of recurrent or refractory primary central nervous system lymphoma." (PMID 39777345, 2024). "Recent studies have demonstrated that treatment regimens incorporating BTK inhibitors, such as zanubrutinib, can safely and effectively treat both systemic high-risk DLBCL and primary central nervous system lymphoma (PCNSL)." (PMID 38813246, 2024). "Given the superior BBB penetration of JDB175 compared to currently approved BTK inhibitors, it is essential to evaluate the activity of BTK inhibitors in combination with these agents in future clinical trials for the inhibition of CNS lymphoma." (PMID 37929016, 2023). "In summary, this study has discovered that JDB175, a novel and highly selective BTK inhibitor, exhibits therapeutic activity against CNS lymphoma with excellent BBB penetration and favorable safety profile." (PMID 37929016, 2023). "For example, tumor infiltrating macrophages can be repolarized into M1 in mouse central nervous system lymphoma by combination of Selinexor and BTK inhibitors." (PMID 37964302, 2023). "Recent insights into the pathophysiology of CNS lymphoma have identified the Bruton's tyrosine kinase (BTK) signaling pathway as a potential target." (PMID 37929016, 2023). "BTK inhibitors have been utilized in clinical trials for the treatment of CNS lymphoma and have shown promising and impressive responses." (PMID 37929016, 2023). "BTK inhibitors have been investigated in the treatment of CNS lymphomas in clinical trials and showed promising therapeutic options." (PMID 36465385, 2022). "Our case shows that the novel BTK inhibitor zanubrutinib exhibit specific activity for CNS lymphomas." (PMID 33996600, 2021). "Tirabrutinib (ONO/GS-4059; Ono Pharmaceutical) is a newly developed drug that selectively and irreversibly inhibits Bruton's tyrosine kinase (BTK) and has been approved in Japan for treating relapsed/refractory primary central nervous system lymphoma (PCNSL)." (PMID 33902692, 2021). "Considering the therapeutic activity of bruton tyrosine kinase (BTK) inhibitors for CNS lymphomas, the patient was administered oral zanubrutinib 80 mg daily (given the concurrent administration of posaconazole for preventing fungal infection) on day +382." (PMID 33996600, 2021). "Targeted drugs such as Bruton’s tyrosine kinase (BTK) inhibitors, interleukin-1 receptor-associated kinase-4 inhibitors, and immunomodulators including lenalidomide and pomalidomide had also show certain efficacy in central nervous system lymphoma." (PMID 40978033, 2025). "Numerous clinical trials have investigated the therapeutic potential of combining BTK inhibitors with other drugs for CNS lymphoma treatment, including chemotherapy agents, immune checkpoint inhibitors, PI3K/AKT/mTOR inhibitors, immunomodulatory imide drugs, and various multi‐agent combinations." (PMID 37929016, 2023). "Some clinical trials have shown impressive responses to BTK inhibitors in CNS lymphoma." (PMID 37929016, 2023). "The first-generation BTK inhibitor ibrutinib has shown promising results for CNS lymphoma." (PMID 33996600, 2021). "A feature stemming from its molecular design that separates NX‐5948 from other BTK‐targeted proteolysis‐targeting chimeras (PROTACs) is its ability to cross the blood–brain barrier and degrade BTK intracranially, translating to preclinical efficacy in CNS lymphomas." (PMID 40619749, 2025).
CNS lymphoma (continued). "However, brain exposure to ibrutinib and two other approved BTK inhibitors is low, and the penetration rates (%, Cmax,brain/Cmax,plasma) are all below 10%, which may hinder their efficacy in treating CNS lymphoma." (PMID 37929016, 2023). "Based on this background, we focus on a new potential oral inhibitor of Bruton’s tyrosine kinase (BTK), which has been explored as a novel therapeutic option against CNS lymphomas." (PMID 36465385, 2022). "In this study, we discovered that JDB175, a novel and highly selective BTK inhibitor, exhibits excellent BBB penetration capabilities and demonstrates favorable activity in a mouse model of CNS lymphoma while showing no significant signs of toxicity." (PMID 37929016, 2023).
multiple sclerosis (29 papers, 2019 to 2026). A progressive autoimmune disorder affecting the central nervous system resulting in demyelination. "Due to its involvement in both innate and adaptive immune compartments, BTK has emerged as a promising therapeutic target in autoimmune disorders associated with maladaptive B-cell and myeloid cell responses such as rheumatoid arthritis, systemic lupus erythematosus and multiple sclerosis (MS)." (PMID 39465429, 2024). "Inhibitors of Bruton tyrosine kinase (BTK) are actively being pursued as potential disease-modifying therapies for multiple sclerosis (MS), as attested by several completed or ongoing Phase 3 clinical trials." (PMID 42134274, 2026). "Here, we investigated the role of BTK in human and mouse myeloid cells in the context of multiple sclerosis by in vitro and in vivo studies." (PMID 40607415, 2025). "The use of BTK inhibitors to treat CNS inflammatory disorders are being actively investigated, including multiple sclerosis (MS) and neuromyelitis optica spectrum disorders (NMOSD)." (PMID 39744694, 2025). "There are currently six BTK inhibitors being studied as a possible new drug for treating multiple sclerosis (MS)." (PMID 38638671, 2024). "Bruton’s tyrosine kinase (BTK) inhibitors are an emerging class of therapeutics in multiple sclerosis (MS)." (PMID 38638671, 2024). "Due to its involvement in both innate and adaptive immune compartments, BTK inhibitors have emerged as a therapeutic option in autoimmune disorders such as multiple sclerosis (MS)." (PMID 39465429, 2024). "Considering the good performance of BTK inhibitor in autoimmune arthritis and multiple sclerosis, we chose to focus on the effect of BTK inhibitor on NMOSD." (PMID 38129902, 2023). "Inhibition of BTK has been an emerging treatment option in multiple sclerosis (MS) considering the role of B cells and microglia in pathways contributing to both acute inflammation and chronic disease worsening." (PMID 38022591, 2023). "BTK inhibitors (BTKi) are an emerging oral treatment option for patients suffering from multiple sclerosis (MS)." (PMID 37633912, 2023). "BTK inhibition is an emerging treatment of multiple sclerosis based on completed and ongoing phase II and III clinical trials." (PMID 38022591, 2023). "Recent clinical trials have shown promising results for the next-generation Bruton’s tyrosine kinase (BTK) inhibitor evobrutinib in the treatment of multiple sclerosis (MS)." (PMID 35852869, 2022). "BTK inhibitors have demonstrated efficacy for multiple sclerosis —via an anti-inflammatory mechanism—and have also reduced binge drinking in mice." (PMID 34880215, 2021). "Interestingly, a recent clinical trial indicated that BTK inhibition decreases disease flares in multiple sclerosis patients, but the evidence for the role of BTK in autoimmune and inflammatory disorders is sporadic." (PMID 40432438, 2025). "Selective BTK inhibitors (BTKi) have shown efficacy in clinical trials in multiple sclerosis (MS)." (PMID 40607415, 2025). "Expression of BTK in different white matter lesions in multiple sclerosis." (PMID 38022591, 2023). "Bruton’s tyrosine kinase (BTK) is an emerging target in multiple sclerosis (MS)." (PMID 37438842, 2023). "Inhibition of Bruton’s tyrosine kinase (BTK) is an emerging multiple sclerosis (MS) therapy." (PMID 38022591, 2023). "Multiple sclerosis was tested in phase 2 trials with two BTK inhibitors (evobrutinib and tolebrutinib), both of which demonstrated positive disease impact on this neurodegenerative disorder and are covalent modifiers of BTK." (PMID 34803999, 2021). "The development of novel therapy classes such as Bruton’s tyrosine kinase (BTK) inhibitors, which target disability progression independent of relapses and largely independent of new lesion formation, requires a reappraisal of strategies in the treatment of multiple sclerosis (MS)." (PMID 40985012, 2025).
multiple sclerosis (continued). "This was also conducted for the six BTK inhibitors in phase II or III trial for MS, using the search terms ‘Multiple Sclerosis’ and ‘BIIB091’, ‘evobrutinib’, ‘fenebrutinib’, ‘orelabrutinib’, ‘remibrutinib’ and ‘tolebrutinib’." (PMID 38638671, 2024). "Inhibition of Bruton’s tyrosine kinase (BTK) using BTK inhibitors (BTKis) is being actively pursued as a novel non-depleting B-cell targeting approach in patients with multiple sclerosis (MS)." (PMID 35303161, 2022).
primary immunodeficiency (25 papers, 2010 to 2025). "XLA is a primary immunodeficiency caused by different mutations in the gene encoding Bruton’s tyrosine kinase (BTK), which alter B-cell development." (PMID 41517428, 2025). "Germline mutations in Bruton's tyrosine kinase (BTK) have been implicated in the primary immunodeficiency disease X‐linked agammaglobulinaemia, through its essential role in B lymphocyte development." (PMID 32608058, 2020). "X-linked agammaglobulinaemia (XLA) is a rare inherited primary immunodeficiency disease characterized by the B cell developmental defect, caused by mutations in the gene coding for Bruton’s tyrosine kinase (BTK), which may cause serious recurrent infections." (PMID 31830942, 2019). "XLA is a primary immunodeficiency disease caused by a severe block of B cell development at the pre-B to immature B cell stage that is induced by mutations of the human Bruton’s tyrosine kinase (BTK) gene." (PMID 25316352, 2014). "Since Dr. Ogden Bruton’s 1952 paper describing the first human primary immunodeficiency disease, the peripheral membrane binding signaling protein, aptly named Bruton’s tyrosine kinase (BTK), has been the target of intense study." (PMID 34249912, 2021). "Among the remaining ones, it is of note the gene set linked to primary immunodeficiency given that it includes genes related to CLL biology such as Zap70, CD19, BTK and CD79A genes." (PMID 27611921, 2016).